R3HDML (R3H domain containing like)
Description:
Putative serine protease inhibitor.
Synonyms: dJ881L22.3
Tractability: Antibody: UniProt places it where antibodies can reach, with high confidence; UniProt predicts a signal peptide or a membrane-spanning region; its Gene Ontology location is reachable by antibodies, with medium confidence.
Gene: Protein-coding gene on chromosome 20 (44,337,043 to 44,351,238, forward strand). Ensembl gene ENSG00000101074.
Subcellular location: Secreted
Subcellular location (Human Protein Atlas): Cytosol; Nucleoplasm; Predicted to be secreted
Gene Ontology:
Cellular component: extracellular region
Genetic constraint (gnomAD): Loss-of-function variants: 19 observed, 23.27 expected, observed/expected ratio (o/e) 0.82, 90% interval 0.57 to 1.2. The upper end of that interval is the gene's LOEUF score, 1.2, which puts it in group 5 of 6, group 1 being the genes least tolerant of losing a copy. Missense variants: 298 observed, 353.43 expected, observed/expected ratio (o/e) 0.84, 90% interval 0.77 to 0.93. Synonymous variants: 133 observed, 137.53 expected, observed/expected ratio (o/e) 0.97, 90% interval 0.84 to 1.12.
Homologues: Orthologues: chimpanzee R3HDML (99% identical), macaque R3HDML (94% identical), pig R3HDML (84% identical), rabbit R3HDML (84% identical), rat R3hdml (79% identical), mouse R3hdml (78% identical), guinea pig R3HDML (67% identical), tropical clawed frog r3hdml (60% identical), zebrafish r3hdml (50% identical), Drosophila melanogaster CG32679 (25% identical), Caenorhabditis elegans scl-15 (24% identical), Caenorhabditis elegans scl-12 (23% identical), and 41 more. Paralogues in human: PI15 (55% identical), CRISPLD2 (47% identical), CRISPLD1 (45% identical), CLEC18A (28% identical), CLEC18B (28% identical), CLEC18C (28% identical), GLIPR1L1 (27% identical), GLIPR1 (26% identical), CRISP3 (24% identical), GLIPR1L2 (23% identical), CRISP1 (23% identical), CRISP2 (22% identical), and 1 more.
Diseases named in the same sentence as R3HDML in open-access papers:
R3HDML is named in the same sentence as 3 diseases in open-access papers, as found by Europe PMC text mining. Sharing a sentence is not in itself a finding about the gene and the disease. The quoted sentences say what the papers report.
colon tumor (1 paper, 2022). "A subcluster of genes encoding proteases (PRSS33), protease inhibitors (R3HDML), and cytoskeletal factors (TNNC2) was overexpressed only in colon tumor tissues and resembled the expression pattern of LY6G6D." (PMID 35953834, 2022).
schizophrenia (1 paper, 2011). A major psychotic disorder characterized by abnormalities in the perception or expression of reality. "Roles in fertilization, spermatogenesis, and pathogen response have all been proposed for CRISP proteins, but these mechanisms are not immediately supportive of R3HDML as a schizophrenia candidate gene." (PMID 22220189, 2011).
carcinoma (1 paper, 2022). A malignant tumor arising from epithelial cells. "Of note, in classical carcinomas, there was coamplification and overexpression of the R3HDML, TNNC2, and DUSP15 locus at chromosome band 20q11-13, suggesting functional cooperation between these coamplified genes." (PMID 35953834, 2022).